KRTAP16-1 (keratin associated protein 16-1)
Synonyms: KAP16.1
Tractability: No criterion of Open Targets' tractability assessment is met for any kind of drug.
Gene: Protein-coding gene on chromosome 17 (41,307,700 to 41,309,309, reverse strand). Ensembl gene ENSG00000212657.
Pathways (Reactome):
Developmental Biology: Keratinization
Gene Ontology:
Molecular function: structural molecule activity
Cellular component: cytosol; keratin filament
Genetic constraint (gnomAD): Loss-of-function variants: 0 observed, 0.58 expected, observed/expected ratio (o/e) 0, 90% interval 0 to 1.82. That is too few expected variants to judge how well the gene tolerates losing a copy. Missense variants: 675 observed, 675.07 expected, observed/expected ratio (o/e) 1, 90% interval 0.94 to 1.07. Synonymous variants: 262 observed, 255.79 expected, observed/expected ratio (o/e) 1.02, 90% interval 0.93 to 1.13.
Homologues: Orthologues: chimpanzee KRTAP16-1 (98% identical), mouse Krtap16-1 (70% identical), rat Krtap16-1 (69% identical), guinea pig KRTAP16-1 (66% identical), macaque KRTAP16-1 (59% identical), dog KRTAP16-1 (25% identical). Paralogues in human: KRTAP10-7 (21% identical), KRTAP10-9 (20% identical), KRTAP10-4 (20% identical), KRTAP10-6 (20% identical), KRTAP10-11 (20% identical), KRTAP10-12 (19% identical), KRTAP10-10 (18% identical), KRTAP10-3 (17% identical), KRTAP10-5 (17% identical), KRTAP10-1 (17% identical), KRTAP10-8 (17% identical), KRTAP10-2 (17% identical), and 35 more.